SNHG10 (small nucleolar RNA host gene 10)
Synonyms: FLJ40557; NCRNA00063; LINC00063; TP53LC16; C14orf62
Gene: Long non-coding RNA gene on chromosome 14 (95,521,937 to 95,534,925, reverse strand). Ensembl gene ENSG00000247092.
Gene Ontology:
Biological process: RNA processing
Cellular component: Cajal body; nucleolus
Diseases named in the same sentence as SNHG10 in open-access papers:
SNHG10 is named in the same sentence as 27 diseases in open-access papers, as found by Europe PMC text mining. Sharing a sentence is not in itself a finding about the gene and the disease. The quoted sentences say what the papers report.
osteosarcoma (10 papers, 2021 to 2025). A usually aggressive malignant bone-forming mesenchymal neoplasm, predominantly affecting adolescents and young adults. "Small nucleolar RNA host gene 10 (SNHG10), a newly identified long non-coding RNA, has been reported to promote the osteosarcoma proliferation and invasion by wnt/beta-catenin signaling." (PMID 40495890, 2025). "SNHG10 also plays an important role in the progression of prostate cancer, lung cancer, and osteosarcoma." (PMID 36871072, 2023). "SNHG10 was also reported to regulate glucose uptake and lactate production via increasing the methylation of the miR-218 gene in osteosarcoma." (PMID 35422758, 2022). "SNHG10 has been identified as oncogenic in bladder cancer, hepatocellular carcinoma, osteosarcoma, glioma, non–small cell lung cancer, acute myeloid leukemia, and gastric cancer." (PMID 36105077, 2022). "Consistently, higher expression level of SNHG10 is also observed in osteosarcoma cell lines, including MG-63, SW-1353, U-2OS, Sasos-2, HOS, and 143B, when compared with osteoblastic cell line hFOB1.19." (PMID 34130697, 2021). "SNHG10 has been reported to be an oncogenic lncRNA of gastric cancer, liver cancer, osteosarcoma, and other malignancies." (PMID 34432955, 2021). "SNHG10 was reported to be involved in the glucose metabolism in osteosarcoma via increasing the methylation of miR-218." (PMID 34613933, 2021). "Additionally, SNHG10 upregulates frizzled class receptor 3 (FZD3) to maintain the activation of the Wnt/β-catenin signaling pathway in osteosarcoma." (PMID 35149697, 2022). "In addition, SNHG10 has reported to promote cell proliferation in osteosarcoma via increasing glucose uptake and miR-218 gene methylation." (PMID 34676212, 2021). "For instance, SNHG10 promotes cell proliferation and invasion in osteosarcoma." (PMID 34676212, 2021). "Moreover, SNHG10 promoted osteosarcoma tumorigenesis in xenograft tumor model." (PMID 34130697, 2021). "Similarly, another recent study showed that small nucleolar RNA host gene 10 (SNHG10) was markedly overexpressed in osteosarcoma compared with adjacent healthy counterparts by quantitative real time polymerase chain reaction (qRT-PCR) and fluorescence in situ hybridization (FISH) analysis." (PMID 34130697, 2021).
gastric cancer (9 papers, 2020 to 2022). A primary or metastatic malignant neoplasm involving the stomach. "To further validate the role of CAMK2N1, SNHG10, and hsa-miR-378a-3p in GC, we assessed the expression of mRNA and protein in gastric cancer cell lines." (PMID 36092901, 2022). "We found that SNHG10 was highly expressed in gastric cancer lines, and the miR-378a-3p was lowly expressed in BGC-823, HGC-27, and MKN-45." (PMID 36092901, 2022). "SNHG10 facilitates gastric cancer cell proliferation and migration by targeting the miR-495/CTNNB1 axis and activating the WNT pathway." (PMID 34676212, 2021). "PBX3 stabilized by SNHG10/DDX54 increases the migration of gastric cancer and activates SNHG10 expression via positive feedback." (PMID 33050646, 2020). "SNHG10 was shown to be overexpressed in gastric cancer (GC) cells." (PMID 35422758, 2022). "Previously, SNHG10 has been reported to exert an oncogenic function in several cancer types like hepatocellular carcinoma (HCC) and gastric cancer (GC)." (PMID 33298070, 2020).
hepatocellular carcinoma (8 papers, 2020 to 2022). A malignant tumor that arises from hepatocytes. "In hepatocellular carcinoma, SNHG10 upregulates the expression of c-Myb and promotes the proliferation, migration, invasion and EMT of cancer cells." (PMID 35149697, 2022). "Recently, SNHG10 has been identified as having a tumor facilitator role in hepatocellular carcinoma and gastric carcinoma." (PMID 34676212, 2021). "The novel TCPOBOP-inducible lncRNAs include lnc4278/Dancr, lnc14777/Snhg1, and lnc10895/Snhg10, which promote hepatocellular carcinoma through their actions as miRNA sponges, and lnc733/Gas5, which is also a miRNA sponge and acts to inhibit liver fibrosis." (PMID 33761883, 2021). "SNHG10 is known to be over-expressed in hepatocellular carcinoma, and we found it facilitates hepatocarcinogenesis and metastasis." (PMID 32646427, 2020). "Similarly, high expression of SNHG10 was related to overall survival in hepatocellular carcinoma and non-small cell lung cancer." (PMID 34676212, 2021).
liver cancer (6 papers, 2020 to 2022). An epithelial or non-epithelial malignant neoplasm that arises from the liver. "SNHG10 functions as an oncogenic lncRNA overexpressed in liver cancer and positively regulates carcinogenesis and metastasis." (PMID 34613933, 2021). "It is reported that SNHG10 was upregulated in liver cancer and formed a positive feedback loop with its homolog SCARNA13, thereby promoting cancer metastasis." (PMID 33081752, 2020). "In liver cancer, SNHG10 is overexpressed and forms a positive feedback loop with SCARNA13 to promote carcinogenesis and tumor metastasis." (PMID 32843060, 2020). "SNHG10 was also shown to be a predictor of poor survival in patients with liver cancer." (PMID 35506202, 2022). "SNHG10 was recently shown to play an oncogenic role in liver cancer." (PMID 35506202, 2022). "SNHG10 has been characterized as an oncogenic lncRNA in liver cancer." (PMID 33081752, 2020). "In liver cancer, SNHG10 was upregulated and predicts poor survival." (PMID 32843060, 2020). "A recent study reported that SNHG10 was an oncogenic lncRNA in liver cancer." (PMID 33081752, 2020). "In addition, SNHG10 regulates the expression of SOX9 to promote cell invasion, proliferation, migration and epithelial–mesenchymal transition in liver cancer, suggesting its role as an oncogenic lncRNA." (PMID 32843060, 2020). "Therefore, SNHG10 is likely a tumor suppressor lncRNA in NSCLC, and SNHG10 may play different roles in different types of cancer, suggesting that NSCLC and liver cancer may have different molecular pathogenesis." (PMID 33081752, 2020).
glioma (5 papers, 2020 to 2022). A benign or malignant brain and spinal cord tumor that arises from glial cells (astrocytes, oligodendrocytes, ependymal cells). "Next, we wanted to know the mechanism underlying SNHG10-mediated influences on glioma cell functions." (PMID 33298070, 2020). "For example, SNHG10 exerted oncogenic functions in glioma by sponging miR-532-3p and enhancing FBXL19 expression." (PMID 34676212, 2021). "In this study, SNHG10 was found to be up-regulated in glioma cells, and it facilitated cell growth, stemness, migration and invasion in glioma, which is consistent with the findings in HCC and GC." (PMID 33298070, 2020). "Conclusively, ETS1 acted as a transcription activator of SNHG10 and exhibited oncogenic properties via SNHG10/miR-532-3p/FBXL19 axis in glioma." (PMID 33298070, 2020). "Through conducting caspase 3/8/9 activity detection and TUNEL assay, we certified the facilitative effect of ETS1 knockdown on glioma cell apoptosis, while such impact was then rescued by SNHG10 up-regulation, miR-532-3p repression or FBXL19 overexpression." (PMID 33298070, 2020). "Subsequently, we discovered that the down-regulation of SNHG10 decreased the colony formation ability while up-regulation of SNHG10 increased such ability in both the two kinds of glioma cells." (PMID 33298070, 2020). "More importantly, ETS1 promoted the transcription of SNHG10 and it mediated contribution to the malignant behaviors of glioma cells by SNHG10/miR-532-3p/FBXL19 signaling." (PMID 33298070, 2020). "Our study found that SNHG10 was an oncogene in glioma and it accelerated the malignant phenotypes of glioma cells by targeting miR-532-3p/FBXL19 axis." (PMID 33298070, 2020). "The main task of our study was to investigate the function and molecular mechanism of SNHG10 in glioma." (PMID 33298070, 2020). "In this study, we validated the cytoplasmic localization of SNHG10 in glioma cells, and found miR-532-3p as the downstream molecule of SNHG10." (PMID 33298070, 2020). "Moreover, SNHG10 facilitates malignant behaviors and stemness of glioma cells by targeting the miR-532-3p/F-box and leucine rich repeat protein 19 (FBXL19) axis." (PMID 35149697, 2022). "Likewise, SNHG10 knockdown hampered cell invasion while its overexpression accelerated cell invasion in glioma." (PMID 33298070, 2020). "Moreover, TUNEL assay results displayed that the apoptosis rate of glioma cells was remarkably elevated in response to the down-regulation of SNHG10." (PMID 33298070, 2020). "Further, we probed the function of ETS1 in glioma and whether its regulatory role was mediated by SNHG10/miR-532-3p/FBXL19 pathway." (PMID 33298070, 2020). "Furthermore, it was found that FBXL19 targeted by miR-532-3p facilitated cell growth and stemness in glioma, and that SNHG10 worked in glioma by increasing FBXL19 expression through sequestering miR-532-3p." (PMID 33298070, 2020). "Taken all together, SNHG10 contributed to the malignant behaviors of glioma cells in vitro." (PMID 33298070, 2020). "Furthermore, we designed and conducted rescue assays to validate the regulatory role of SNHG10/miR-532-3p/FBXL19 axis in glioma." (PMID 33298070, 2020). "Moreover, miR-532-3p was validated to bind with SNHG10 and expressed at a low level in glioma cells." (PMID 33298070, 2020). "Hence, subcellular fractionation and FISH assays were exploited to assess the localization of SNHG10 in glioma cells." (PMID 33298070, 2020). "However, present work still lacks clinical supports and in-depth animal studies to further validate the importance of SNHG10/miR-532-3p/FBXL19 axis in glioma, and these two aspects will be further focused on in our future research." (PMID 33298070, 2020). "Moreover, whether targeting SNHG10 will be developed into a new method for treating patients with glioma still needs to be further evidenced in the future." (PMID 33298070, 2020). "In short, miR-532-3p could bind to SNHG10 and hinder the progression of glioma." (PMID 33298070, 2020).
glioma (continued). "Also, the downstream mechanism whereby FBXL19 works as a tumor-contributor in glioma, and whether SNHG10 functions in glioma through other pathways, need to be further uncovered in future studies." (PMID 33298070, 2020). "In this study, we aimed to investigate whether SNHG10 mediated ceRNA network in glioma." (PMID 33298070, 2020). "Finally, we explored the upstream of SNHG10 in glioma cells." (PMID 33298070, 2020). "SNHG10 was transcriptionally activated by ETS1 and played an oncogenic role in glioma by sponging miR-532-3p and up-regulating FBXL19." (PMID 33298070, 2020). "As a result, ETS1/SNHG10/miR-532-3p/FBXL19 axis was discovered, which might provide a helpful theoretic basis for the exploration of new targets for glioma therapy." (PMID 33298070, 2020). "SNHG10 is a novel lncRNA which has not been explored in glioma." (PMID 33298070, 2020).
prostate carcinoma (5 papers, 2021 to 2023). A carcinoma that arises from epithelial cells of the prostate gland. "SNHG10 is expressed at higher levels in prostate cancer tissue than in normal tissue, contributing to a shorter survival time among patients." (PMID 36344648, 2022). "SNHG10 is a long non-coding RNA (lncRNA) found to be overexpressed in multiple human cancers including prostate cancer (PC)." (PMID 34676212, 2021). "However, the role of SNHG10 in prostate cancer hasn’t been mentioned." (PMID 34613933, 2021). "In addition, we compared the expression of SNHG10 between normal and prostate cancer in GSE70770, and found that SNHG10 was over-expressed in cancer tissues (P < 0.001)." (PMID 34676212, 2021).
lung cancer (3 papers, 2022 to 2023). A malignant neoplasm involving the lung. "SNHG2, SNHG3, and SNHG10 are expressed at low levels in lung cancer tissues, while other SNHGs are upregulated in lung cancer tissues." (PMID 38104110, 2023).
non-small cell lung carcinoma (3 papers, 2021 to 2022). A group of at least three distinct histological types of lung cancer, including non-small cell squamous cell carcinoma, adenocarcinoma, and large cell carcinoma. "For example, linc01207 regulates ARHGAP11A and promotes the progression of non-small cell lung cancer by secreting mir-525-5p; long noncoding RNA, SNHG10, promotes the malignant progression of colorectal cancer cells by targeting mir-3690." (PMID 35647035, 2022).
ovarian carcinoma (3 papers, 2024 to 2025). A malignant neoplasm originating from the surface ovarian epithelium. "As a tumor-suppressive lncRNA, SNHG10 expression is decreased in ovarian cancer tissues, and its low expression is associated with inferior overall survival and progression-free survival of affected patients." (PMID 39967908, 2025). "Another study showed that the low expression of SNHG10 is also associated with poor prognosis of ovarian cancer patients." (PMID 41200835, 2025). "Three SNHGs, including SNHG2, SNHG9, and SNHG10, have been found to play a protective role in ovarian cancer." (PMID 41200835, 2025). "According to reported studies, in addition to SNHG2, SNHG5, SNHG9, and SNHG10, most SNHGs play a role as a proto-oncogene in the occurrence and progression of ovarian cancer via different pathways." (PMID 41200835, 2025). "Previous research has indicated that decreased expression of SNHG10 is correlated with a poor prognosis in ovarian cancer patients." (PMID 39045330, 2024). "The overexpression of SNHG10 has been shown to suppress the proliferation, colony formation, migration, and invasion of ovarian cancer cells." (PMID 39045330, 2024). "Mechanically, SNHG10 combines with miR-200a-3p to form an RNA-induced silencing complex (RISC), which can act with tumor suppressor bridging integrator−1(BIN1), subsequently suppressing the proliferation and EMT of ovarian cancer cells." (PMID 41200835, 2025).
pancreatic cancer (3 papers, 2022 to 2025). "CASC8, DNMBP-AS1, LINC00941, TM4SF1-AS1, and UCA1 expression was positively correlated with risk scores, indicating that they are risk factors for pancreatic cancer; in contrast, SNHG10 and SOCS2-AS1 were negatively correlated, thus serving as protective factors for pancreatic cancer." (PMID 36871072, 2023). "The results showed that AL161431.1, LINC00663, LINC00941, and SNHG10 were highly expressed in pancreatic cancers samples; in particular, AL161431.1 and LINC00663 had significantly higher levels." (PMID 35647035, 2022). "AL161431.1, LINC00663, LINC00941, and SNHG10 expressions in pancreatic cancer cells were relatively higher as compared to the normal cells." (PMID 35647035, 2022). "Further screening identified five pancreatic cancer-specific epi-lncRNA genes (AL161431.1, LINC00663, LINC00941, SNHG10, and TM4SF1-AS1), which were used to construct a prognostic model." (PMID 40264765, 2025). "Further, the five pancreatic cancer-specific epi-lncRNA genes (AL161431.1, LINC00663, LINC00941, SNHG10, and TM4SF1-AS1) were identified." (PMID 35647035, 2022). "The RT-PCR result confirmed that AL161431.1, LINC00663, LINC00941, and SNHG10 expressions in pancreatic cancer samples were higher as compared to normal pancreatic samples; the expression of TM4SF1-AS1 in pancreatic cancer cells was significantly lower than that in normal pancreatic samples." (PMID 35647035, 2022). "Survival analysis of pancreatic cancer samples showed that low expression of UCA1, TM4SF1-AS1, LINC00941, DNMBP-AS1, and CASC8 improved OS more than high expression, whereas high expression of SNHG10 and SOCS2-AS1 improved OS more than low expression (P < 0.001)." (PMID 36871072, 2023).
bladder cancer (2 papers, 2021 to 2022). "Jiang found that SNHG10, SNHG12, and LINC00115 were abnormally expressed in bladder cancer and that downregulation of SNHG12 expression was related to the inhibition of tumor proliferation." (PMID 34641864, 2021).
colorectal cancer (1 paper, 2022). A primary or metastatic malignant neoplasm that affects the colon or rectum. "SNHG10 can promote tumor progression in colorectal cancer and acute myoid leukemia (AML) through microRNA interaction." (PMID 35647035, 2022).
gastric tumors (1 paper, 2023). "For instance, SNHG10 promotes the growth and migration of gastric tumors by targeting the miR-495-3p/CTNNB1 axis, activating the WNT pathway and the DDX54-mediated PBX3 feedback pathway." (PMID 36871072, 2023).
Insulin resistance (1 paper, 2025). Increased resistance towards insulin, that is, diminished effectiveness of insulin in reducing blood glucose levels. "Given the regulatory role of miR-378b in insulin resistance and organ fibrosis, we hypothesize that SNHG10 may play a role in DN by regulating miR-378b." (PMID 40495890, 2025).
ischemic stroke (1 paper, 2024). A stroke disorder caused by obstruction of blood flow to the brain, due to thrombotic (local blood clot formation) or embolic (due to a blood clot or other material traveling from another site) event. "Implications of the SNHG10/miR-665/RASSF5/NF-κB pathway in dihydromyricetin-mediated ischemic stroke protection." (PMID 39726744, 2024). "In conclusion, this study provides significant insights into the neuroprotective mechanisms of DHM in ischemic stroke, particularly through modulation of the SNHG10/miR-665/RASSF5 axis." (PMID 39726744, 2024). "This study aims to elucidate the role of SNHG10 in the pathology of ischemic stroke, specifically its regulatory effects on miR-665 and related inflammatory and oxidative stress pathways, providing insights into potential therapeutic strategies of DHM for OGD/R-induced injury in SH-SY5Y cells." (PMID 39726744, 2024). "Our findings reveal a novel regulatory axis, SNHG10/miR-665/RASSF5, which modulates neuroinflammation and oxidative stress in ischemic stroke, suggesting this axis as a promising therapeutic target." (PMID 39726744, 2024).
lymph node metastasis (1 paper, 2022). "In addition, lymph node metastasis, intraperitoneal metastasis and SNHG10 expression were found to be significantly correlated with the OS of EOC patients." (PMID 35149697, 2022).
pancreatic adenocarcinoma (1 paper, 2021). "There are significant associations between SNHG10 expression and OS or PFS in adrenocortical carcinoma (ACC), bladder urothelial carcinoma (BLCA), kidney renal clear cell carcinoma (KIRC), liver hepatocellular carcinoma (LIHC), pancreatic adenocarcinoma (PAAD), and thymoma (THYM)." (PMID 34676212, 2021).